RNU6-757P (RNA, U6 small nuclear 757, pseudogene)
Gene: Small nuclear RNA gene on chromosome 5 (134,715,483 to 134,715,582, forward strand). Ensembl gene ENSG00000222266.
Homologues: Orthologues: chimpanzee U6 (99% identical), macaque U6 (94% identical), dog U6 (66% identical). Paralogues in human: RNU6-1060P (89% identical), RNU6-116P (89% identical), RNU6-744P (89% identical), RNU6-12P (88% identical), RNU6-13P (88% identical), RNU6-24P (88% identical), RNU6-266P (88% identical), RNU6-32P (88% identical), RNU6-33P (88% identical), RNU6-41P (88% identical), RNU6-44P (88% identical), RNU6-742P (88% identical), and 1284 more.